FUT9 (fucosyltransferase 9)
Diseases named in the same sentence as FUT9 in open-access papers (continued):
Sharing a sentence is not in itself a finding about the gene and the disease.
tumor (11 papers, 2017 to 2025). "Strikingly, the expression of genes associated with cancer stemness was greatly enhanced in the FUT9+ tumor cluster compared to the remaining clusters." (PMID 32927726, 2020). "In contrast, lymph node metastases had greater tumor cell diversity including novel tumor states enriched with gene signatures associated with cancer stemness and metastasis (e.g., DKK2, FUT9, DIAPH321–23)." (PMID 41279557, 2025). "This is in line with the percentage of the FUT9+ primary CRC tumor cells (0.04%, 11/272) identified from our scRNA seq reanalysis." (PMID 32927726, 2020). "Defining the cancer-specific biosynthetic properties of FUT4 and FUT9 is fundamental for the interpretation of the biological functions that these enzymes exert within a tumor cell." (PMID 30476078, 2019). "This indicates that FUT9 downregulation is a tumor‐transformative event only if occurs at later stages of tumor progression." (PMID 29196508, 2017). "This further supports a notion that as tumors develop, FUT9 activity is switched off in the bulk of tumor cells to enhance their aggressiveness, which should negatively affect patient survival." (PMID 29196508, 2017). "Our results indicate that FUT9 activity promotes the expansion of TICs, while its downregulation supports expansion and aggressiveness of bulk of tumor cells." (PMID 29196508, 2017). "Additionally, the fact that FUT9+ normal cells clustered away from the FUT9+ tumor cells highlights the existence of major transcriptional programs differentiating these two cell subsets." (PMID 32927726, 2020). "Therefore, we employed a classification into FUT9+ and FUT9− normal or tumor epithelial cell clusters." (PMID 32927726, 2020). "Moreover, we observed an upregulation of target genes downstream of these TFs in FUT9+ human CRC tumor cells." (PMID 32927726, 2020). "Together our data indicate that FUT4 and FUT9 may have overlapping, yet also unique biosynthetic properties regarding the modification of the substrate N-glycome in tumor cells." (PMID 30476078, 2019). "Finally, in primary CRC FUT9+ tumor cells pathways related to cancer stemness were enriched, providing a clinically meaningful annotation of the complicity of FUT9 in stemness regulation and may open new avenues for therapeutic intervention." (PMID 32927726, 2020). "Thus, while FUT9 downregulation benefits the bulk of tumor cells its activity may support the subpopulation of cancer stem cells or tumor‐initiating cells (TICs) that play a central role in tumor development." (PMID 29196508, 2017). "Focusing on glycosyltransferases expression in tumor tissues, we observed two distinct expression clusters, segregating FUT3, FUT4, FUT6, and ST3GAL4 transcripts, from FUT7, FUT9, ST3GAL3, and ST3GAL6." (PMID 39508360, 2025). "By immunohistochemistry analysis, we found that the expression of FUT9 was upregulated in ESCC tissues and related to tumor progression." (PMID 37674363, 2023). "FUT9-mediated hyperfucosylation also triggered Sox2, ALDH, and CD44 expression and tumor sphere formation." (PMID 37298124, 2023). "Another interesting observation was that FUT9+ tumor cells did not cluster together, indicating that stem-like FUT9+ cells display differential gene expression profiles." (PMID 32927726, 2020). "This may reflect the dual functionality of FUT9 where it supports tumor development by enhancing TIC activity, while inhibiting the expansion of the bulk of tumor cells." (PMID 29196508, 2017). "Interestingly, the Yy1 gene regulatory network seemed to be mostly FUT9-specific, but not tumor-specific." (PMID 32927726, 2020). "Since our experimental data suggest that FUT9 provides an advantage for TIC populations, while its reduced activity benefits other tumor cells, its relative abundance should be expected to gradually drop with tumor progression, mirroring a decrease in the proportional representation of TICs." (PMID 29196508, 2017).
tumor (continued). "Although the function of FUT9 in tumors not perfectly clear, a previous study showed that suppression of its two gene family orthologs, FUT1 and FUT4, greatly impeded the tumor development, suggesting a potential oncogenic role of this gene." (PMID 35939448, 2022).
cancer (10 papers, 2012 to 2025). A tumor composed of atypical neoplastic, often pleomorphic cells that invade other tissues. "Moreover, the loss of FUT9 augmented the ability of cancer cells to form colonies in monolayers, when cells were seeded at very low densities." (PMID 29196508, 2017). "Since the FUT9 enzyme and its synthesized product, the Lewisx glycan structure, are expressed in embryonic and neuronal stem cells, we hypothesized that their expression might also be associated with stemness in the context of cancer." (PMID 32927726, 2020). "Through RNA-seq, FUT9, a glycosyltransferase reported to affect cancer stem-like properties in many cancers, attracted our attention." (PMID 37674363, 2023). "Ultimately, this study warrants future research on the tumorigenic role of FUT9 in other cancer types and its potential exploitation as a CSC-specific biomarker for therapeutic targeting." (PMID 32927726, 2020). "Downregulation of both these genes has been previously shown to lead to enhanced cell migration and invasion, resulting in aggressive cancers, consistent with our results showing FUT9 knockdown leads to increased colony formation and cell migration." (PMID 29196508, 2017). "This pinpoints reactions whose flux is predicted to be most afflicted by FUT9 inactivation in advanced‐stage cancer." (PMID 29196508, 2017). "FUT9 exhibited a high frequency of genomic alterations across pan-cancer types." (PMID 40084262, 2025). "Additionally, the expression levels of both ELF4 and FUT9 were significantly positively correlated with the expressions of the cancer stemness markers CD44 and CD133." (PMID 37674363, 2023). "Furthermore, ectopically expressed FUT9 dramatically rescued the inhibitory effects ofELF4 knockdown on the proliferation, migration, invasion, and cancer stemness of ESCC cells." (PMID 37674363, 2023). "After lentiviral vectors carrying FUT9 cDNA were transfected, the inhibitory effects ofELF4 knockdown on cancer stemness could also be significantly rescued." (PMID 37674363, 2023). "Meanwhile, ELF4 is verified to affect ESCC cancer stemness by regulating FUT9 expression." (PMID 37674363, 2023). "This classification further underscores the role of FUT9 in cancer stemness induction." (PMID 32927726, 2020). "This analysis revealed that the loss of FUT9 at early stages does not bring the metabolic state close to that observed in advanced cancer." (PMID 29196508, 2017). "Noteworthy, several candidate susceptibility genes (PRKCA, BMP6, ADAMTS19, ARHGAP6, FUT9/8, FAM108C1, CHL1, BTBD9 and WDR52) are involved in the actin cytoskeleton arrangement, cell adhesion and cell motility processes, which are important for cancer invasion and metastasis." (PMID 22532847, 2012). "There was a strong possibility that ELF4 augmented ESCC cancer stem-like properties and further accelerated ESCC progression by transcriptionally regulating the expression of FUT9." (PMID 37674363, 2023). "Although FUT9+ cells did not cluster together, we tested multiple signatures related to cancer stemness and pluripotency." (PMID 32927726, 2020). "In addition to the observed positive correlation between ELF4 or FUT9 and the cancer stemness-related markers CD44 and CD133, our immunohistochemistry results revealed a significant positive correlation between the expressions of ELF4 and FUT9." (PMID 37674363, 2023). "Following this approach, we successfully generated FUT4- or FUT9-expressing MC38 glyco-engineered cell lines and examined changes in their respective glycosylation profiles, focusing on biosynthesis of the fucosylated Lewisx determinant and its impact on the cancer cell glycome." (PMID 30476078, 2019).
FUT9 also shares sentences with these, for which no sentence is quoted: colon polyps (2 papers); infection (2); schizophrenia (2); breast carcinoma (1); colorectal polyps (1); colorectal tumors (1); dengue (1); leukemia (1); lung adenocarcinoma (1); lung carcinoma (1); melanoma (1); meningioma (1); myoclonic epilepsy (1); non-small cell lung carcinoma (1); pancreatic cancer (1); squamous cell carcinoma (1).